SOX2 (SRY-box transcription factor 2)
Diseases named in the same sentence as SOX2 in open-access papers (continued):
Sharing a sentence is not in itself a finding about the gene and the disease.
tumor (continued). "SOX2 overexpression induces tumor progression, recurrence and metastasis in many cancers, including NSCLC." (PMID 35059870, 2022). "The expression of Sox2 gene in laryngeal squamous Hep-2 cells was higher on 1 kPa substrate than that on 8 kPa substrate, indicating a higher stem like ability of tumor cells on 1 kPa." (PMID 36419159, 2022). "In SS, the expression of stem cell transcription factor SOX2 and its histone H3K27me3 triggered by mutations in the SS18-SSX driver caused tumor development." (PMID 35151264, 2022). "The tumor sizes, tumor growth curves, and weights showed that circSOX2 suppressed the growth of SOX2-amplified LUSC." (PMID 36243874, 2022). "IL6 and CXCL8 present MSCs culture-conditioned media induced expression of OCT4 and SOX2 in colorectal cancer cells and promoted tumor progression via adenosine monophosphate protein kinase (AMPK)-mediated NF-κB activation." (PMID 35629138, 2022). "These tumor have a distinctive IHC profile (loss of SMARCA4/BRG1, loss of SMARCA2/BRM, and expression of stem-cell markers SALL4, CD34, SOX2), although SOX2 is also commonly positive in NECs." (PMID 34663914, 2022). "Intriguingly, growth inhibition by elevated SOX2 did not significantly disrupt the cell cycle distribution of engineered SOX2-inducible (i-SOX2) tumor cells." (PMID 35454854, 2022). "Isolated Sox2-expressing murine tumor cells had a greater tumor-initiating potential compared to Sox2-negative cells." (PMID 35892887, 2022). "While we did not observe a difference in VEGFA levels between the DSG2‐high and DSG2‐low patients in the non‐MS cohort, other genes associated with tumour vascularization (e.g. SOX4 and SOX2) were co‐expressed with DSG2." (PMID 34245117, 2022). "To identify common mechanisms through which SOX2 elevation restricts tumor cell proliferation, we initially performed RNA-seq using two diverse tumor cell types." (PMID 35454854, 2022). "SOX2 expression is binary, while its accumulation is a dynamic process; tumor cells accrue varying levels of SOX2 as they actively proliferate." (PMID 35737114, 2022). "To identify potential mechanisms driving the growth-inhibitory effects of elevated SOX2, we performed RNA-seq using two diverse tumor cell types to identify genes and pathways affected in common." (PMID 35454854, 2022). "Considering its importance in stem cells, SOX2 has also been studied in cancer to determine its potential role in tumor initiation, maintenance and targeted therapy." (PMID 35162954, 2022). "Stemness markers, SOX2 and nestin, were differentially expressed in tumor cells at the invasive margin." (PMID 35312755, 2022). "The TF-protein, SOX2, has been found to be a tumor promoter and has a dynamic therapeutic strategy for TNBC." (PMID 36567949, 2022). "The studies presented here set out to determine the mechanisms through which SOX2 elevation restricts tumor cell proliferation." (PMID 35454854, 2022). "We found that CD133 and SOX‐2 were up‐regulated in U251 cells and xenograft tumor tissue treated with rRIP2 or transfected with RIP2 plasmids." (PMID 36184801, 2022). "More importantly, the expression of integrin αvβ3 was found in abundant tumor cells/tissues, whereas the expression of SOX2 was only found in those cancer stem cells, which accounted for a little proportion in tumor cells." (PMID 35473511, 2022). "Even though both ATRT-SHH and MYC tumors arise from Smarcb1-negative Sox2-positive precursor cells, Sox2 expression levels in the tumor itself vary between the tumor subgroups of both murine and human samples." (PMID 35318328, 2022). "Targeting the molecular pathways in CSCs and downregulation of CD133, Nanog, Oct3/4, and Sox2 have been crucial steps to control the tumor progression." (PMID 36325671, 2022). "Increasing evidence suggests that Oct4 and Sox2 are marker proteins of stem cells and tumor stem cells, which are essential for the maintenance of tumor stem cell stemness." (PMID 35927251, 2022).
tumor (continued). "Transcription factor SOX2-expressing MSCs were presented in the CRC-associated CAFs population, which stimulated tumor progression." (PMID 34971821, 2022). "High levels of SOX2 have also been observed in lung and colorectal tumor cells that display higher tumor-initiating capacities and decreased growth rates compared with SOX2low cells within the tumor." (PMID 35454854, 2022). "Physically, STAT3 interacts with NF in tumor and tumor-associated immune cells, wherein lactoglobule-EGF Factor 8 (MGF-E8)/STAT3, Sonic Hedgehog/EGFR/STAT3/Sox2 pathways, and CSC-like phenotypes were promoted by tumor-associated macrophages." (PMID 36061200, 2022). "In an “in vivo study”, SOX2 expression in HNSCC tumor cells led to a decrease in CD8+ T-lymphocyte infiltration and promoted tumor growth through the suppression of stimulation of interferon genes (STING)-dependent interferon-I-mediated signaling." (PMID 36359251, 2022). "SOX2 expression was observed in differentiated and less differentiated tissue layers alike, including the stratum basale and tumour cells resembling a basal-like phenotype." (PMID 35296132, 2022). "All these data suggest that siSOX2 rescues resistance to cisplatin in NSCLC, which makes SOX2 a new target for sensitizing NSCLC tumor cells to cisplatin." (PMID 35059870, 2022). "More importantly, we further demonstrated that TRIB3 interacted with AKT1 to up-regulate FOXO1 and SOX2 expression, which was indispensable for the pro-tumor effects induced by integrin αvβ3." (PMID 35473511, 2022). "This allowed to directly visualize the quiescent Prom1+ or Sox2+ cells within the tumor and characterize their localization in the core or infiltrating edge tumor areas." (PMID 35970913, 2022). "The results demonstrated that YTHDC1 was significantly and positively correlated with BMI1 and SOX2 mRNA expression levels in HNSCC tumor cells, and that cells with high YTHDC1 expression coexpressed stemness pathway-related genes." (PMID 36411870, 2022). "Through OPN-induced myCAF transformation and tumor microenvironment crosstalk, cancer stemness marker expression (Oct4, Nanog, and Sox2) and human breast cancer metastasis are highly increased." (PMID 36284815, 2022). "It has been well documented that SOX2 can promote tumor proliferation and invasion and can regulate tumor cell stemness in a hypoxic microenvironment through a variety of pathways." (PMID 35918393, 2022). "γH2AX analysis was performed on sagittal sections of the right hemisphere, which includes the corpus callosum and striatum, and on coronal sections of the OB, each co-stained for Sox2 to identify tumor cells." (PMID 36482431, 2022). "Silenced SOX2 can inhibit proliferation and induce loss of tumorigenicity in GBM tumour‐initiating cells in immunosuppressant mice, and knockdown studies of SOX2 reduced cellular proliferation and colony formation in a GBM cell line." (PMID 34953010, 2022). "In this context, SOX2 expression was found sufficient to promote cancer stem cell marker expression, tumor cell self-renewal in vitro, and tumor growth in vivo." (PMID 35456049, 2022). "CSCs express transcription factors (e.g., Nanog, Oct4, and Sox2) initially detected in ES cells and exhibit pluripotent differentiation properties into various functional cells able to reconstitute the complete tumor mass." (PMID 35582537, 2022). "We observed a wide range of percentage of SOX2 + nuclei among samples, and variability from area to area within the same tumor." (PMID 36333778, 2022). "Most of the tumor cells were exclusively positive for SOX2 or Ki-67 in immunohistochemistry and immunofluorescence." (PMID 35055392, 2022). "The results of IHC exhibited that the expression of CD3, CD8, cGAS and STING were reduced in SOX2‐expressing tumours." (PMID 35415876, 2022). "Our finding that elevated SOX2 restricts tumor cell proliferation reflects the effects of high SOX2 expression during development and cancer." (PMID 35454854, 2022).
tumor (continued). "Serial sections were used to spatially interrogate antigen expression of vimentin, VCAM-1, CD31, Ki67, nestin, and SOX2 in both tumor cells and the adjacent stroma, specifically at the tumor core, tumor rim, and contralateral striatum." (PMID 35312755, 2022). "The tumor cells were stained positively for some neurogenic makers, for instance S100, Syn, MAP2, NFP, Nestin, CD56, and SOX2, which highlighted the neural lineage differentiation of tumor cells." (PMID 36153506, 2022). "An extraordinary high expression rate of Sox2 is detected in GB with about 80–85% positive tumor cells." (PMID 35183162, 2022). "Subsequently, an increasing number of studies have shown that overexpression of SOX2 is closely related to tumour invasiveness and poor prognosis." (PMID 34953010, 2022). "They restore Let-7 expression and suppress tumor oncogenes such as SOX2 in cancer cells and show strong inhibitory effects on cancer cell stem-like phenotypes." (PMID 36428779, 2022). "The positive expression of Ki67 and NANOG, OCT4, and SOX2 proteins was found to be decreased in the tumor tissues of mice treated with Exos-sh-NC, which was further reduced in the presence of Exos-sh-ALKBH5." (PMID 36551544, 2022). "In our results, CSCs highly expressed tumor stemness marker genes, SOX2 and NANOG, ZNF and ZBTB families." (PMID 36451812, 2022). "SOX2+Nestin+ cells were abundant within the tumor boundary but only sporadically outside of the tumor." (PMID 36038950, 2022). "Our in vitro data suggests that FMOD and SOX2 cooperation plays an important role in tumor vasculogenic mimicry." (PMID 35737114, 2022). "Previous studies from our laboratory have shown that the inducible elevation of SOX2 reversibly inhibits the proliferation and tumor growth of multiple cancer cell types." (PMID 35454854, 2022). "Previous studies established that high levels of SOX2 in both fetal and tumor cells restrict cell proliferation and induce a slowly cycling state." (PMID 35454854, 2022). "The oncogenic role of SOX2 is confirmed further by several studies exhibiting SOX2 dependent alteration of cell growth, invasion ability, and chemo-resistant activity beyond tumor types." (PMID 35629138, 2022). "Accordingly, the percentage of CD44+ cells and SOX2+ cells reduced in tumor spheroids upon MEX3A knockdown, while they increased upon MEX3A overexpression." (PMID 36276637, 2022). "SOX2 histochemical staining was much greater in tumor tissues from mice on the high-fat diet than those on the control isocaloric diet." (PMID 35884514, 2022). "Given the well-established role of SOX2 in tumor-initiating cells, we experimentally demonstrated the parallel relationship between CHRNA7 and SOX2 when CHRNA7 is either knocked down or overexpressed." (PMID 33603170, 2021). "In line with changes in SOX2 expression, higher expression levels of Bcl-2 were also coordinated with tumor grade (p = 0.003) and the progression of the tumor (p = 0.04)." (PMID 34436030, 2021). "A combination of caveolin-1 and Sox-2 protein levels was sufficient to maintain high predictive accuracy, which we validated in tumor samples from patients with HNSCC with known clinical response to cetuximab." (PMID 34546978, 2021). "Lewis X, the markers of stemness (CD44 expression, ALDH, Sox2), and tumor-sphere formation, chemoresistance to 5-FU treatment, and proliferation of tumor in vivo were increased in FUT9-expressing murine colon adenocarcinoma cells compared with control cells." (PMID 34948129, 2021). "BMI1 and SOX2 have been sought as novel molecular targets for preventing tumor metastasis and recurrence." (PMID 33499351, 2021).
tumor (continued). "Altogether, our data highlight different aspects of the role of SOX2 following loss of p27, according to cellular context, and uncover an unexpected SOX2-dependent tumor-promoting role for SCs." (PMID 33574062, 2021). "Results of the Western blot analysis also showed increased expression of Bmi1 and Sox2, which are markers for tumor-initiating cells, in the drug resistant cells." (PMID 34681918, 2021). "The critical role of the SOX2+ cell population in these tumors was further demonstrated with the finding that SOX2+ cells exhibited substantially higher tumor-initiating capacity than SOX2− cells." (PMID 35054230, 2021). "Sox2 overexpression not only increased the expression of β-catenin but also enhanced tumor aggressiveness." (PMID 34199293, 2021). "Ten of the 12 cases stained positively for SOX2 which was seen in the nucleus and the cytoplasm of tumor cells, as well as the nucleus of stromal cells adjacent to tumor glands, in nine of 10 cases." (PMID 34685477, 2021). "Using TMAs constructed from human GBM formalin-fixed paraffin-embedded tumor samples (n = 89), we used semiquantitative immunohistochemistry to analyze the level of protein expression of SOX2 and FOXO3." (PMID 36303712, 2021). "MiR-145 was established as a tumor suppressor, targeting embryonic transcription factors including Lin28, Nanog, Sox2, and Oct4, and also inhibiting the EMT key regulator, ZEB1 expression." (PMID 34760707, 2021). "Sex-determining region Y-box2 (SOX2), a master regulator of embryonic and induced pluripotent stem cells (iPSCs), drives cancer stemness, fuels tumor initiation, and contributes to tumor aggressiveness." (PMID 33953166, 2021). "In conclusion, while cell transformation in p27−/− melanotrophs is known to be cell autonomous, we demonstrate here that SOX2 is required in these cells for tumor development in p27−/− mutants." (PMID 33574062, 2021). "A significant association was found for both SOX2 and Bcl-2 overexpression with TNM staging (p = 0.02, p = 0.04) and tumor grading (p = 0.01, p = 0.003), respectively." (PMID 34436030, 2021). "Western blot analysis of whole tumor extracts demonstrated decreased expression of the human-specific GSC markers SOX2 and OLIG2 and reduced levels of p-STAT3 compared with the controls." (PMID 33986188, 2021). "(J) Representative images of Sox2 and Oct4 stained tumor sections from HCC1806-derived tumors from control and treatment groups." (PMID 34889737, 2021). "Of note, the expression of the stem cell marker SOX2 increased in the tumor treated with MTX alone, suggesting that overreacting conversion from non-GSCs to GSCs occurred in response to the exhaustion of GSCs caused by MTX." (PMID 34769063, 2021). "We evaluated the staining for SOX2, a marker of NSCs and progenitors, in response to tumor proximity." (PMID 34268110, 2021). "A study uncovered that it is noticeably reduced in tumor stem cells and its exogenous expression in cervical cancer suppresses SOX2, thereby reducing bulk of tumor stem cells." (PMID 34733825, 2021). "After overexpression of Sox2, the cell cycle progressed into the G2/M + S phase and promoted tumour growth." (PMID 33762574, 2021). "Exogenous overexpression of Usp9x in SK-Mel29 cells lead to upregulation of SOX2 and as expected, increased 3D tumor growth." (PMID 33613844, 2021). "The relation between Sox2 expression and the clinical aggression of different tumor types, including breast, lung, and prostatic cancers, was observed by several studies." (PMID 34567804, 2021). "In many cancers, Sox2 and Oct4 are inappropriately activated, leading to aberrant expression of downstream target genes, which stimulates tumor growth and tumor recurrence." (PMID 33916244, 2021). "A previous study indicated that β-catenin is a transcription partner for SOX2, and that the combination of SOX2 with β-catenin promotes the transcriptional activity of each other in breast cancer." (PMID 33953166, 2021).
tumor (continued). "Sox2 amplification is positively correlated with increased proliferation, tumor burden metastasis, and poor prognosis." (PMID 34195082, 2021). "Suggested that Usp9x activity and expression were elevated in metastatic as compared to primary tumor and correlated with elevated SOX2 levels." (PMID 33613844, 2021). "This cell subset showed increased expression of OCT4, NANOG, and SOX2 and tumor-sphere formation ability." (PMID 34778245, 2021). "As a result, SOX2 overexpression promotes and maintains the stemness of CSCs, which confirms its role in oncogenesis and tumor progression in HCC." (PMID 34436030, 2021). "Treatment of these tumor-bearing mice with vismodegib or cytarabine (Ara C) targeted the proliferating population and spared the infrequently proliferating SOX2+ cell population." (PMID 35054230, 2021). "The epigenetic modifications like hypermethylation or demethylation of H3K9 alter the expression of Sox2, changing the self‐renewing capabilities of these tumorigenic tumor‐repopulating cells." (PMID 33754478, 2021). "The expression of stem cell markers such as ALDH1, BMI-1, CD44, Nanog, and SOX2 is well-investigated for other tumour entities, and has shown promising results as prognostic parameters with potential as a target for cancer treatment." (PMID 33009929, 2021). "Meanwhile, we found that both PHB KO and PHB inducible-KD resulted in a pronounced reduction of SOX2+ or Olig2+ tumor cells in GBM xenografts, suggesting a decrease of GSC pool in PHB-deleted tumors." (PMID 34140524, 2021). "Nicotine induces the expression of the embryonic stem cell factor SOX2 via the NACHR-YAP1-E2F1 signaling axis that maintains the characteristic of NSCLC tumor stem cells." (PMID 34796198, 2021). "Elsewhere, there were tumour regions where SOX2-positive tumour cells appeared to be mostly BTK-negative." (PMID 34645618, 2021). "As a well-known biomarker for stem-like cells, SOX2 is upregulated in a wide range of cancers to support tumour proliferation and metastasis, and elevated SOX2 levels are associated with drug resistance." (PMID 34539663, 2021). "The results showed that miR-3065-3p overexpression in HCT116 cells led to an increase in the expression of the stem cell markers NANOG, OCT4 and SOX2 in tumor tissue." (PMID 34656128, 2021). "We found that IL20RA overexpression boosted the expression of the stemness marker genes Nanog and Sox2 in tumor tissues in vivo and increased the number of lung metastatic foci." (PMID 33456560, 2021). "Subsequently, we tested the effect of SOX2 on tumor growth in nude mice bearing HepG2 cell tumors expressing sh-SOX2, miR-222-5p agomir or corresponding controls (sh-NC or agomir-NC)." (PMID 33952719, 2021). "This decrease in tumour-initiating capacity was mediated through reduced activation of Sox2, a key regulator of stem cell gene transcription." (PMID 34503199, 2021). "Since the tumor sphere formation and the expression of Nestin and SOX2 are the characteristics of GSCs, these results suggest that RPS6 plays critical roles in the development and maintenance of GSCs." (PMID 35008473, 2021). "Western blotting of tumor tissues demonstrated efficient SOX2/Nestin suppression in SB273005 or SB273005/TMZ groups compared to the control or TMZ group." (PMID 33408794, 2021). "Group 2 was characterised by tumour samples exhibiting low expression of BMI-1/CD44 and high expression of ALDH1/Nanog/SOX2 associated with a lower grading." (PMID 33009929, 2021). "The expression level of OCT4, SOX2, and Nanog remains high in glioblastoma-derived circulating tumor cells, making them resistant to temozolomide and gamma radiation therapy." (PMID 35008527, 2021). "The inhibition of GSK3b reduces self-renewal potential, tumour sphere formation and the mRNA expression of the stem cell markers Sox2, Oct4, and Nanog leading to the induction of cell differentiation." (PMID 34831291, 2021).